MIR6500 (microRNA 6500)
Synonyms: hsa-mir-6500
Gene: MicroRNA gene on chromosome 1 (51,060,018 to 51,060,103, forward strand). Ensembl gene ENSG00000275816.
Homologues: Orthologues: chimpanzee MIR6500 (100% identical).